CFAP77 (cilia and flagella associated protein 77)
Description:
Microtubule inner protein (MIP) part of the dynein-decorated doublet microtubules (DMTs) in cilia axoneme, which is required for motile cilia beating.
Synonyms: C9orf171; FLJ46082
Tractability: Small molecule: a structure with a bound ligand is known.
Gene: Protein-coding gene on chromosome 9 (132,410,043 to 132,573,319, forward strand). Ensembl gene ENSG00000188523.
Subcellular location: Cytoplasm, cytoskeleton, cilium axoneme; Cytoplasm, cytoskeleton, flagellum axoneme; Cell projection, cilium
Gene Ontology:
Molecular function: protein binding
Biological process: flagellated sperm motility
Cellular component: axonemal microtubule; axoneme; cilium; axonemal B tubule inner sheath; sperm flagellum
Genetic constraint (gnomAD): Loss-of-function variants: 22 observed, 28.76 expected, observed/expected ratio (o/e) 0.77, 90% interval 0.55 to 1.09. The upper end of that interval is the gene's LOEUF score, 1.09, which puts it in group 4 of 6, group 1 being the genes least tolerant of losing a copy. Missense variants: 375 observed, 386.33 expected, observed/expected ratio (o/e) 0.97, 90% interval 0.89 to 1.06. Synonymous variants: 151 observed, 150.77 expected, observed/expected ratio (o/e) 1, 90% interval 0.88 to 1.15.
Homologues: Orthologues: chimpanzee CFAP77 (100% identical), dog CFAP77 (89% identical), pig CFAP77 (89% identical), mouse Cfap77 (88% identical), guinea pig CFAP77 (87% identical), rat Cfap77 (85% identical), macaque CFAP77 (61% identical), tropical clawed frog cfap77 (43% identical), zebrafish cfap77 (33% identical).
Diseases named in the same sentence as CFAP77 in open-access papers:
CFAP77 is named in the same sentence as 2 diseases in open-access papers, as found by Europe PMC text mining. Sharing a sentence is not in itself a finding about the gene and the disease. The quoted sentences say what the papers report.
ciliopathy (1 paper, 2023). A genetic disorder of the cellular cilia or the cilia anchoring structures, the basal bodies, or of ciliary function. "Thus, the phenotype of a CFAP77-KO might be more severe in the case of other species and a potential ciliopathy gene in humans." (PMID 37061538, 2023).
opioid dependence (1 paper, 2022). "Further, two genes with differential mCpHs in OUD, RERE, and CFAP77, were previously identified in an epigenome-wide association study from our group evaluating differential 5mC associated with opioid dependence in whole blood samples from European–American women (n = 220)." (PMID 36745154, 2022).